LDB3 (LIM domain binding 3)
Diseases named in the same sentence as LDB3 in open-access papers:
LDB3 is named in the same sentence as 51 diseases in open-access papers, as found by Europe PMC text mining. Sharing a sentence is not in itself a finding about the gene and the disease. The quoted sentences say what the papers report.
cardiomyopathy (26 papers, 2009 to 2026). A disease of the heart muscle or myocardium proper. "These symptoms are shared by several heart congenital diseases, such as myofibrillar myopathy 4, dilated cardiomyopathy 1X and 2F, as well as early-onset myopathy with fatal cardiomyopathy, whose causal genes are LDB3, FKTN, BAG5 and TTN, respectively." (PMID 41583011, 2025). "Further, LDB3 stabilizes sarcomere structures in cardiac muscle by binding α-actinin, and mutations within LDB3 have already been associated with various types of cardiomyopathies." (PMID 38639887, 2024). "In this report, we provide molecular and clinical data demonstrating that recessive loss-of-function LDB3 variants lead to a severe early-onset cardiomyopathy with additional skeletal muscle involvement likely dependent on the location of the variant." (PMID 36253531, 2023). "LDB3 is a protein stabilizing the sarcomere during contraction in cardiac and skeletal muscles, and mutations in this protein have been linked to severe cardiomyopathies." (PMID 37627638, 2023). "In conclusion, we find that recessive loss-of-function LDB3 variants can lead to an early-onset and lethal human phenotype of cardiomyopathy and myopathy." (PMID 36253531, 2023). "Mutations in the LDB3 gene have been identified in some cardiomyopathies, such as DCM, HCM, and LVNC." (PMID 28821295, 2017). "LDB3 is crucial in maintaining z-disk integrity and is associated with cardiomyopathies including following mechanical stress and, interestingly, increased LDB3 phosphorylation downstream of P38 MAPK has been suggested to play a potential role in pathological cardiac remodelling." (PMID 40753091, 2025). "In humans, autosomal dominant missense variants in LDB3 that affect only short isoforms are associated with skeletal myopathies, while variants affecting only long isoforms are primarily associated with cardiomyopathies; however bi-allelic or loss-of-function LDB3 variants have yet to be reported." (PMID 36253531, 2023). "PDZ motif-containing protein-related myofibrillar myopathy Z disc-associated, alternatively spliced (ZASP-MFM) is a rare autosomal dominant or late-onset distal myopathy with related cardiomyopathy, which is produced by mutations of LIM domain-binding 3/Z band alternatively." (PMID 40757566, 2023). "LDB3 variant can cause cardiac dysfunction such as myofibrillar myopathy, DCM, arrhythmia and cardiomyopathy, as well as arrhythmia right ventricular dysplasia (ARVD)." (PMID 36721086, 2023). "Autosomal dominant variants in LDB3 (also known as ZASP), encoding the PDZ-LIM domain-binding factor, have been linked to a late onset phenotype of cardiomyopathy and myofibrillar myopathy in humans." (PMID 36253531, 2023). "It has been suggested that the subtype of cardiomyopathy is determined by the variant type and site location as seen for other cardiomyopathy-associated genes (e.g., DES, LDB3, BAG3, FHL1)." (PMID 33802723, 2021). "Mutations in LDB3, encoding LIM domain binding protein-3, which is also known as cipher or ZASP, cause myofibrillar myopathy and different cardiomyopathies in humans." (PMID 32670084, 2020). "Mutations in LDB3 gene have been also associated with muscular dystrophy and several cardiomyopathies (arrhythmogenic right ventricular, noncompaction and dilated cardiomyopathies)." (PMID 41583011, 2025). "Mutation in the LDB3 gene can be associated with cardiomyopathy, dilated, with or without left ventricular noncompaction myopathy, myofibrillar myopathy, and familial isolated dilated cardiomyopathy, and late-onset distal myopathy." (PMID 40757566, 2023). "In the family of our study, the parents carrying with only SYNE1 p.S4607F or LDB3 p.M456R/MYH6 p.S180Y mutations presented with no phenotype of cardiomyopathy or arrhythmia." (PMID 33949037, 2021). "Cardiomyopathy is usually very late and only seen in a minority of patients, which may be due to extremely low expression of LDB3 isoforms containing the exon 6 in heart." (PMID 33742095, 2021).
cardiomyopathy (continued). "Finally, we also identified four variants of uncertain significance in cardiomyopathy-associated genes (TNNT2, PRDM16, LDB3, and SDHA) in three fetuses." (PMID 33553264, 2020). "This case presents the phenotypic expression of two heart conditions, congenital LVA and prominent LV trabeculation, coexisting with LDB3 gene mutation, suggesting the same genetic background may be shared within congenital LVA and cardiomyopathies." (PMID 28821295, 2017). "For example, the presence of congenital heart disease could possibly be ascribed to the deregulation of the DES, LDB3, POPDC2 and SLC4A3 genes, all of which have previously been associated with cardiac function and pathology, such as cardiomyopathy." (PMID 23816241, 2013). "Genes associated with ER stress (e.g., ATF4, NUPR1, DDIT3, TRIB3, CHAC1, SESN2, HERPUD1) were upregulated and genes related to cardiomyopathy and sarcomeric structure (e.g., MYH7, SYNPO2L, LDB3, ACTN2, MYLK3) were downregulated by afatinib, sorafenib, or high-dose ponatinib." (PMID 37069550, 2023).
dilated cardiomyopathy (15 papers, 2013 to 2025). Cardiomyopathy which is characterized by dilation and contractile dysfunction of the left and right ventricles. "Mutation and aberrant splicing of LDB3 were demonstrated in dilated cardiomyopathy and myotonic dystrophy type 1." (PMID 40099963, 2025). "Mutations in the Ldb3 gene are responsible for myofibrillar myopathy and dilated cardiomyopathy in humans." (PMID 23586671, 2013). "The known disease caused by mutations in the LDB3 gene is dilated cardiomyopathy." (PMID 37907926, 2023). "Mutations in LDB3 cause several forms of heart disease including dilated cardiomyopathy." (PMID 27276052, 2016). "As discovered in dilated cardiomyopathy, LDB3 may participate in Z‐line maintenance in the tunica media layer of the aorta, and its alteration or aberrant splicing may play a major role in the pathogenesis of TAAD." (PMID 40099963, 2025). "Additionally, two VUS in the genes TPM1 (related to hypertrophic cardiomyopathy) and LDB3 (related to hypertrophic cardiomyopathy and dilated cardiomyopathy) were detected in the genetic testing." (PMID 33919104, 2021). "LDB3 and PDLIM5 have both been implicated in dilated cardiomyopathy DCM." (PMID 26061177, 2015).
myofibrillar myopathy (7 papers, 2013 to 2024). "In all SAMP strains except SAMP8/TaSlc, we detected a p.R473W missense mutation in the Ldb3 gene, which has been associated with myofibrillar myopathy." (PMID 23586671, 2013). "In all SAMP strains except SAMP8, we detected a p.R473W missense mutation in the Ldb3 gene, which has been associated with myofibrillar myopathy." (PMID 23586671, 2013).
hypertrophic cardiomyopathy (6 papers, 2016 to 2023). "Intrudingly, we identified Pdlim3 and Ldb3 as oxygen-sensitive genes that are associated with hypertrophic cardiomyopathies." (PMID 35326510, 2022). "For example, TCAP (regulates sarcomere assembly and titin assembly; implicated in familial hypertrophic cardiomyopathy), MYL3 (myosin light chain 3; implicated in left ventricular hypertrophic cardiomyopathy and restrictive cardiomyopathy), LDB3, and DES were highly downregulated." (PMID 34338636, 2021).
cardiac hypertrophy (5 papers, 2011 to 2024). "Therefore, downregulation of LDB3 could set marked cardiac hypertrophy reaction." (PMID 29438398, 2018).
myotonic dystrophy type 1 (4 papers, 2013 to 2025). Steinert disease, also known as myotonic dystrophy type 1, is a muscle disease characterized by myotonia and by multiorgan damage that combines various degrees of muscle weakness, arrhythmia and/or cardiac conduction disorders, cataract, endocrine damage, sleep disorders and baldness. "For example, RNA sequencing of a sudden death patient revealed an abnormal LDB3 splicing pattern, which is linked to myotonic dystrophy type 1 (DM1), whereas previously performed clinical exome sequencing had identified a variant in RBM20 of unclear significance." (PMID 39982482, 2025). "In vertebrate systems, differential isoform regulation through development has long been appreciated, and in some disease states such as type 1 myotonic dystrophy, fetal or neonatal stage isoforms of Tnnt2, Atp2a1 (Serca1), and Ldb3 (Zasp) are inappropriately expressed." (PMID 34620214, 2021). "In addition, LDB3 exon 4 is aberrantly spliced in myotonic dystrophy type 1." (PMID 23586671, 2013).
left ventricular noncompaction (3 papers, 2015 to 2025). Left ventricular noncompaction (LVNC) is a rare cardiomyopathy characterized anatomically by prominent left ventricular trabeculae and deep intratrabecular recesses causing progressive systolic and diastolic dysfunction, conduction abnormalities, and occasionally thromboembolic events. "One study has reported testing of the LDB3 gene in the case of left ventricular noncompaction (LVNC) with Wolff‐Parkinson‐White syndrome." (PMID 40950385, 2025). "Several variants associated with cardiac disorders were detected, but only the LDB3 gene is directly associated with DCM (LIM domain-binding 3 gene LDB3; Cardiomyopathy, Dilated, 1C; OMIM#601493) and both sisters harbored the same missense variant (c.G352A, p.V118M; rs35507268)." (PMID 26214305, 2015).
arrhythmogenic right ventricular cardiomyopathy (2 papers, 2017 to 2023). "Two of them were described before: DSP variant as unclassified in proband with arrhythmogenic right ventricular cardiomyopathy and MYH7 variant as possibly pathogenic but coexisting with another possibly pathogenic variant in LDB3 gene in proband with familial dilated cardiomyopathy." (PMID 28045975, 2017).
idiopathic dilated cardiomyopathy (2 papers, 2020 to 2024). Decreased function of the heart associated with cardiac enlargement and congestive heart failure, of unknown cause. "LDB3 gene mutations cause idiopathic dilated cardiomyopathy (IDCM) and sometimes occur simultaneously with both prominent left ventricular trabeculation and congenital left ventricular aneurysms." (PMID 32851066, 2020). "Sato et al4 proposed that disruptions in the microcirculation during development may facilitate this abnormal development, whereas Shan et al5 reported on a mutation in the LDB3 or ZASP gene as a cause of congenital LVA, a gene also implicated in cases of idiopathic dilated cardiomyopathy." (PMID 39295811, 2024).
muscular dystrophies (2 papers, 2017 to 2021). "Mutations in TTN and LDB3 genes can cause the abnormal development of the skeletal muscle, leading to muscular dystrophy." (PMID 34698087, 2021). "In addition, some of the genes recently found to be associated with ARVC are also responsible for myopathies/muscular dystrophies, such as DES, LDB3, and TTN." (PMID 28750076, 2017).
channelopathy (1 paper, 2024). Channelopathies are a group of diseases caused by the dysfunction of ion channel subunits or their interacting proteins. "The variants included three channelopathy-associated genes (RYR2, CACNA1C, and ANK2), three HCM- or DCM-associated genes (MYH7, LDB3, and PRKAG2), five ACM-related genes (PKP2, JUP, DSG2, DSP, and TMEM43), and two cardiac transcription factor genes (TBX5 and GATA4)." (PMID 39272661, 2024).
diabetes (1 paper, 2025). "A diabetes-specific targeted analysis showed negatively enriched Z-disc and contractile gene sets enriched due to the downregulation of CASQ2, peripherin (PRPH), nebulette (NEBL), titin-cap (TCAP), and LIM domain-binding proteins LDB3, PDLIM4, and PDLIM5 (Dataset EV36)." (PMID 40759793, 2025).
glaucoma (1 paper, 2022). Increased pressure in the eyeball due to obstruction of the outflow of aqueous humor. "BOD1L1, RALYL, LDB3, ACAD10, CDK11A, and DPF3 are also associated with glaucoma topical treatments (P < 1 × 10−5)." (PMID 36450729, 2022).
ischemic cardiomyopathy (1 paper, 2022). Ischemic cardiomyopathy is a cardiomyopathy in which a weakness in the muscle of the heart due to inadequate oxygen delivery to the myocardium with coronary artery disease being the most common cause. "In this study, we showed that the expression of high MW Ldb3 isoforms decreased in LV of HF patients with ischemic cardiomyopathy, as well as in LV of HF rats in which we have previously observed LV structural alterations, desmin aggregate accumulation, and sarcomere disruption." (PMID 35806378, 2022).
myocardial infarction (1 paper, 2022). Gross necrosis of the myocardium, as a result of interruption of the blood supply to the area, as in coronary thrombosis. "We were therefore interested in studying cardiac Ldb3 expression during HF following myocardial infarction." (PMID 35806378, 2022).
Myotonia (1 paper, 2020). An involuntary and painless delay in the relaxation of skeletal muscle following contraction or electrical stimulation. "A previous study showed that 2-fold upregulation of MBNL1 protein by transduction of a recombinant adeno-associated viral vector reversed missplicing of Clcn1, Ldb3, Serca1, and Tnnt3, resulting in a significant reduction in myotonia in a DM1 mouse model." (PMID 32054946, 2020).
myopathies (18 papers, 2013 to 2025). "Studies of Ldb3Ala165Val/+ mice indicate that the myopathy-associated LDB3 p.Ala165Val mutation triggers early aggregation of filamin C and its chaperones at muscle Z-disc before aggregation of the mutant protein." (PMID 33742095, 2021). "Mutations and abnormal expression of MYBPC2 or LDB3 have been associated with myopathies and cardiopathies, which indicates that cytoskeletal proteins participate in the formation of pathological changes in FHL1 KO mice." (PMID 30083183, 2018). "This PDZ-LIM protein-encoding gene has to date only been reported in association with myopathies; however, a recent study indicated that alternatively spliced LDB3 transcripts are broadly expressed in the central and peripheral nervous systems of humans and mice." (PMID 38994994, 2024). "LDB3 interactors filamin C and myotilin are also expressed in the spinal motor neuron, nerve, and neuromuscular junction, thereby providing the basis for neurogenic manifestations in myopathies associated with mutations in these so-called muscle proteins." (PMID 36609526, 2023). "LDB3 is involved in sarcomere organization, with mutations associated with myopathy." (PMID 26109061, 2015). "Furthermore, Ldb3 variants have been observed to be associated with myopathy in human patients." (PMID 35806378, 2022). "When LDB3 is mutated, PKCα and TSC2-mTOR mediated homeostasis is impaired, leading to protein aggregation myopathy." (PMID 33742095, 2021). "The LDB3 p.Ala165Val mutation impairs PKCα and TSC2-mTOR mediated homeostasis in this large protein assembly leading to protein aggregation myopathy." (PMID 33742095, 2021). "Mutations in DES, CRYAB, FLNC, LDB3, and BAG3 lead to myofibrillar myopathies and/or DCM." (PMID 39684857, 2024). "In addition to LDB3, other rare myopathy gene products such as filamin C and myotilin are expressed in the nervous system [this study; (Mologni13; Xie14)]." (PMID 36609526, 2023). "LDB3 was well known for its role in myofibrillar myopathies." (PMID 34090334, 2021).
cardiac disease (4 papers, 2012 to 2022). "Importantly, this analysis highlighted new potential dystrophin-associated proteins that were specific to cardiac DYS-IPs and involved proteins with known associations to cardiac disease in humans: Cavin-1 (PTRF), Ahnak1 (desmoyokin), Cypher (LDB3, ZASP), and Crystallin alpha B (CRYAB)." (PMID 22937058, 2012).
tumor (4 papers, 2019 to 2025). "Immunohistochemistry of ADAMTS1, DSC1, RNF39, CD3 and LDB3 was performed to evaluate protein expression in tumor cells." (PMID 36333410, 2022).
degenerative diseases (2 papers, 2013 to 2023). "In several SAMP strains, missense mutations were detected in the Prx, Ldb3, and Gja3 genes, which mutations have been found in various human degenerative diseases." (PMID 23586671, 2013). "The expression of LDB3 and interacting proteins in the nervous system indicates expansion of clinical phenotype and genotype relationship in degenerative diseases." (PMID 36609526, 2023).
cancer (1 paper, 2025). A tumor composed of atypical neoplastic, often pleomorphic cells that invade other tissues. "This study develops an a red/far‐red light‐controlled iPSC‐based vaccines (RIVA) based on the chimeric photosensory protein FnBphP and its interaction partner LDB3 for cancer immunotherapy." (PMID 40619603, 2025). "Seeking to improve the immune effect of an iPSC‐based cancer vaccines while minimizing the risk of systemic toxicity, we here developed the RIVA using the chimeric photosensory protein FnBphP and its interaction partner LDB3." (PMID 40619603, 2025).
cardiovascular diseases (1 paper, 2023). "Additionally, some of the predicted genes, including BCL6, LDB3, MUC1 and SYNC, have been implicated in other cardiovascular diseases." (PMID 38100461, 2023).
LDB3 also shares sentences with these, for which no sentence is quoted: distal myopathy (3 papers); Arrhythmia (2); heart failure (2); myotonic dystrophy (2); skeletal myopathies (2); atrial fibrillation (1); axonal neuropathy (1); breast cancer (1); Cardiomyopathy, Dilated, 1C (1); centronuclear myopathy (1); congenital heart disease (1); congenital myopathies (1); COVID-19 (1); familial dilated cardiomyopathy (1); familial hypertrophic cardiomyopathy (1); gastric cancer (1); Hypercalcemia (1); hypertrophy (1); intrinsic cardiomyopathy (1); leukemia (1); muscle disorders (1); nemaline myopathy (1); neuropathy (1); Obesity (1); Onset (1); prostate carcinoma (1); respiratory failure (1); restrictive cardiomyopathy (1); zaspopathy (1).